PLA2G2C (phospholipase A2 group IIC)
Description:
Inactive phospholipase.
Synonyms: UBXN10-AS1
Tractability: Small molecule: a high-quality ligand is known; it belongs to a druggable protein family. Antibody: UniProt places it where antibodies can reach, with high confidence; UniProt predicts a signal peptide or a membrane-spanning region; its Gene Ontology location is reachable by antibodies, with medium confidence. PROTAC: a small molecule that binds it is known.
Target class: Enzyme
Gene: Protein-coding gene on chromosome 1 (20,161,253 to 20,186,518, reverse strand). Ensembl gene ENSG00000187980.
Subcellular location: Secreted
Gene Ontology:
Molecular function: calcium ion binding; phospholipid binding; signaling receptor binding
Biological process: phosphatidylcholine metabolic process; phosphatidylglycerol metabolic process; arachidonate secretion; lipid catabolic process; phospholipid metabolic process
Cellular component: extracellular region
Genetic constraint (gnomAD): Loss-of-function variants: 15 observed, 16.2 expected, observed/expected ratio (o/e) 0.93, 90% interval 0.62 to 1.42. The upper end of that interval is the gene's LOEUF score, 1.42, which puts it in group 5 of 6, group 1 being the genes least tolerant of losing a copy. Missense variants: 139 observed, 163.02 expected, observed/expected ratio (o/e) 0.85, 90% interval 0.74 to 0.98. Synonymous variants: 71 observed, 63.94 expected, observed/expected ratio (o/e) 1.11, 90% interval 0.92 to 1.35.
Homologues: Orthologues: macaque PLA2G2C (85% identical), chimpanzee PLA2G2C (82% identical), dog PLA2G2C (70% identical), rabbit PLA2G2C (70% identical), guinea pig PLA2G2C (68% identical), mouse Pla2g2c (66% identical), rat Pla2g2c (66% identical), Caenorhabditis elegans C03H5.4 (26% identical), Caenorhabditis elegans C07E3.9 (21% identical). Paralogues in human: PLA2G2A (32% identical), PLA2G2F (32% identical), PLA2G2D (30% identical), PLA2G2E (29% identical), PLA2G1B (28% identical), PLA2G10 (27% identical), PLA2G5 (27% identical), OC90 (26% identical).
Diseases named in the same sentence as PLA2G2C in open-access papers:
PLA2G2C is named in the same sentence as 6 diseases in open-access papers, as found by Europe PMC text mining. Sharing a sentence is not in itself a finding about the gene and the disease. The quoted sentences say what the papers report.
allergic bronchopulmonary aspergillosis (1 paper, 2025). Allergic bronchopulmonary aspergillosis (ABPA) is a rare immunologic pulmonary disorder caused by hypersensitivity to Aspergillus fumigatus, clinically manifesting with poorly controlled asthma and recurrent pulmonary infiltrates. "Studies have found high expression of Pla2g4c, Pla2g2c, Pla2g2d, and Pla2g5 in a mouse model of ABPA (allergic bronchopulmonary aspergillosis)." (PMID 40278587, 2025).
colorectal cancer (1 paper, 2008). A primary or metastatic malignant neoplasm that affects the colon or rectum. "Interestingly, the PLA2G2A, PLA2G2C, PLA2G2D, PLA2G2E, PLA2G2F and PLA2G5 genes reside within the same region of human chromosome 1 at p35–36.1, a region frequently altered in colorectal cancer." (PMID 18212756, 2008).
depression (1 paper, 2025). "Following the analysis of the metabolic pathways, seven genes including ALOX5, LTA4H, CYP4Y, PLA2G2C, AKR1C1, AKR1D1 and CYP17A1 were employed to elucidate further the potential mechanisms underlying CS treatment of depression." (PMID 40370520, 2025).
diabetes (1 paper, 2016). "For example, in subjects with prediabetes versus controls, cytochrome P450, family 4, subfamily F, polypeptide 3 (CYP4F3), CYP4F8, Phospholipase A2, group IIC (PLA2G2C), and PLA2G4E were differentially methylated, while in subjects with diabetes versus prediabetes, CYP2E1 and PLA2G12A were involved." (PMID 27555869, 2016).
PLA2G2C also shares sentences with these, for which no sentence is quoted: osteoporosis (1 paper); prediabetes (1).